XPO1 (exportin 1)
Diseases named in the same sentence as XPO1 in open-access papers (continued):
Sharing a sentence is not in itself a finding about the gene and the disease.
lymphoma (continued). "Future research should investigate the role of XPO1-mediated miRNA export in lymphoma, in conjunction with the identification of miRNA targets explore the potential role of an XPO1-miRNA axis NHL growth and treatment resistance." (PMID 36671496, 2023). "In the context of selinexor and the family of SINE molecules in general, further research is needed to better understand XPO1 biology in lymphoma and how this is modulated by selinexor’s ability to inhibit XPO1 function." (PMID 36671496, 2023). "As seen in lymphoma, XPO1-mediated mislocalization prevents these proteins from exerting their anti-cancer functions, which potentially leads to disease progression and chemotherapy resistance." (PMID 36671496, 2023). "Here, we discuss the proteins and RNA transcripts that have been identified as XPO1 cargo in NHL lymphoma including tumour suppressors, immune modulators, and transcription factors, and their implications for oncogenesis." (PMID 36671496, 2023). "In probing the likely mechanism, we identified that XPO1 inhibition significantly reduced the surface expression of HLA-E on lymphoma cell lines and on primary chronic lymphocytic leukemia cells." (PMID 34926302, 2021). "XPO1 overexpression is a common feature among many human cancer types, including lymphoma pancreatic, ovarian, glioma, lung, gastric, prostate, and colorectal cancers, and is associated with poor prognosis." (PMID 34012430, 2021). "In this study, we evaluated the effect of XPO1 inhibition on human NK cell activation against lymphoma cells." (PMID 34926302, 2021). "Our data identifies that XPO1 inhibition sensitizes lymphoma cell lines to NK cell mediated killing via downregulation of HLA-E and subsequent activation of NKG2A+ NK cells." (PMID 34926302, 2021). "Some institutes have used this method to detect somatic mutations including KRAS, XPO1, STAT6 and so on in some solid tumors and lymphomas." (PMID 32284750, 2020). "It has been found that tumor cells and tissues from various tumors including pancreatic, lung, breast, and other cancers and lymphomas express a much higher level of XPO1 protein or mRNA compared to normal cells and tissues." (PMID 31382411, 2019). "High expression of XPO1 has been found in pancreatic, lung, breast and other cancers and lymphomas with a poor prognosis of patients with tumors and high proliferative activity of cancer cells." (PMID 31382411, 2019). "These XPO1 inhibitors demonstrate comparable anti-lymphoma activity to that of a CHOP regimen used on lymphoma xenografts in mice." (PMID 27693556, 2016). "Notably, while XPO1 protein expression has been previously reported in canine DLBCL cells, including the CLBL-1 cell line and cryopreserved tumor cells, as far as we know, this study is the first to report XPO1 mRNA expression in canine lymphoma cells." (PMID 40872651, 2025). "Nonetheless, the results in this study suggest that Exportin 1 could be a promising target for treating lymphoma in dogs." (PMID 40872651, 2025). "We conducted XPO1 gene mutation analysis in the eight canine lymphoma cell lines and found that there were no mutations presented in the coding region of the canine XPO1 gene." (PMID 40872651, 2025). "Additionally, XPO1 enhances the resistance of lymphoma cells to chemotherapy by upregulating the translation of DNA repair proteins." (PMID 38927948, 2024). "EC50 values of selinexor or venetoclax monotherapies in lymphoma cell lines revealed that XPO1 mutant cells SUDHL‐16 XPO1 E571K were significantly more sensitive to selinexor (EC50 = 24 nM) when compared to XPO1 wild‐type (WT) cell lines SUDHL‐6 and Farage (EC50 = 144 nM and 41 nM, respectively)." (PMID 36722323, 2023). "Since rRNA is a component of ribosomal subunits, which are also exported by XPO1, lymphoma cells may be exporting abundant amounts of these translation machineries to aid in the increased expression of oncogenic proteins." (PMID 36671496, 2023).
lymphoma (continued). "XPO1 inhibition potentiates ADCC against lymphoma cells in combination with anti-CD20 monoclonal antibodies rituximab and obinutuzumab in vitro and combining selinexor with ADCC inducing antibodies may lead to increased efficacy in patients." (PMID 36560403, 2022). "XPO1 is located on chromosome arm 2p, a region frequently associated with somatic copy number changes in cancer (e.g., gastric cancer, CLL, lymphomas, neuroblastoma, and rhabdomyosarcoma), and a region that includes putative proto-oncogenes N-MYC, REL, and BCL11A." (PMID 34944778, 2021). "To verify whether the XPO1E571K protein is fully functional, we analysed the localisations of two XPO1 cargoes known to be relevant for lymphoma pathology: nucleophosmin (NPM) and RELA." (PMID 33007990, 2020). "The role of XPO1 in brain metastasis and the notion of using XPO1 inhibitors to suppress CNS involvement of lymphoma may warrant further preclinical examination." (PMID 31752970, 2019). "Notably, in a mouse model of DHL bearing primary tumor cells derived from lymphoma patients, combined treatment with XPO1 and BCL2 inhibitors blocks tumor progression, prevents brain metastasis, and extends host survival." (PMID 31752970, 2019). "Furthermore, data from early phase clinical trials have demonstrated encouraging anti-tumor activities of MDM2 and XPO1 inhibitors in lymphoma patients." (PMID 27626308, 2016). "Our analysis showed that the XPO1 protein expression tended to be high in all the canine lymphoma cell lines examined, suggesting that they could serve as potential therapeutic targets in canine lymphoma cells." (PMID 40872651, 2025). "The XPO1 mRNA and protein expressions in the canine lymphoma cell lines tended to be higher than those in PBMC as normal control, and the XPO1 mRNA expression was well correlated with the XPO1 protein expression." (PMID 40872651, 2025). "Moreover, XPO1 is frequently overexpressed in DLBCL and correlates with poor prognosis, highlighting its significance as a therapeutic target in this aggressive lymphoma subtype." (PMID 38927948, 2024). "It has recently been shown that XPO1 inhibition, in addition to being directly cytotoxic, downregulates HLA-E expression on malignant B cells and promotes NKG2A+ NK cell activation against lymphoma cells." (PMID 36560403, 2022). "To clarify whether high cytoplasmic NR4A1 levels correspond to XPO1 overexpression, we determined the relative XPO1 expression and set it in relation to the occurrence of cytoplasmic NR4A1 in our cohort of aggressive lymphomas." (PMID 30266952, 2018). "Importantly, at least at this stage, the expression levels of XPO1 mRNA or protein do not appear to serve as reliable predictors of KPT-335 sensitivity in canine lymphoma cells." (PMID 40872651, 2025). "Selinexor, an oral, small-molecule selective inhibitor of XPO1-mediated nuclear export (SINE), demonstrated prolonged activity against heavily-pretreated DLBCL without cumulative toxicity and is being investigated as part of an oral, chemotherapy-free regimen for relapsed aggressive lymphoma." (PMID 33202794, 2020).
ovarian carcinoma (30 papers, 2011 to 2025). A malignant neoplasm originating from the surface ovarian epithelium. "Correlations between XPO1 and COX-2 expression have been noted in ovarian cancer, in which XPO1 inhibition reduces COX-2 expression." (PMID 40601866, 2025). "The nuclear export mediator XPO1, also known as CRM1, has gained attention as a critical target in cancer therapy due to its overactivity in various malignancies, including ovarian carcinoma, glioma, osteosarcoma, pancreatic, and cervical cancers." (PMID 39459201, 2024). "Another study revealed that XPO1 expression was increased in cisplatin‐resistant ovarian cancer cells." (PMID 38783482, 2024). "KPT‐185 and KPT‐330 resensitise cisplatin‐resistant ovarian cancer cells to cisplatin by inhibiting XPO1 expression." (PMID 38783482, 2024). "Intriguingly, XPO1 expression is markedly increased in a wide array of tumour cells, including osteosarcoma, glioma, lung cancer, ovarian cancer, pancreatic cancer, oesophageal cancer, gastric cancer and colorectal cancer (CRC) cells." (PMID 38783482, 2024). "Increased expression of the XPO1 correlates with lower survival and with platinum resistance in ovarian cancer and other cancers." (PMID 37760508, 2023). "For example, inhibiting XPO1 diminishes tumor growth and improves the efficacy of cisplatin in ovarian carcinoma." (PMID 36180918, 2022). "In ovarian carcinoma, XPO1 inhibitor inhibited tumor growth and improved the efficacy of cisplatin by nuclear accumulation of FOXO1." (PMID 34384466, 2021). "The early pre-clinical studies in ovarian cancer cells were instrumental in furthering the understanding of XPO1 inhibitors." (PMID 34575598, 2021). "Many hematologic and solid tumors have elevated XPO-1 levels with a strong correlation between increased XPO-1 expression and poor prognosis, as demonstrated in osteosarcoma, pancreatic, lung and ovarian cancers." (PMID 29340049, 2017). "The XPO1 protein is elevated in ovarian carcinoma, glioma, osteosarcoma, pancreatic and cervical cancer." (PMID 25476752, 2014). "Selinexor, a selective inhibitor of exportin 1, additionally provided evidence of efficacy on its own in solid tumor xenografts including kidney, pancreas, prostate, breast, lung, melanoma, colon, gastric, and ovarian cancers, neuroblastoma, and sarcomas." (PMID 39459201, 2024). "Additionally, inhibition of XPO1 with selinexor restored platinum sensitivity in patient-derived ovarian cancer cell lines." (PMID 37760508, 2023). "In addition, XPO1 protein overexpression has been observed in glioma, gastric cancer, ovarian carcinoma, osteosarcoma and other cancers." (PMID 33854580, 2021). "In a human ovarian cancer study, it was found that the overexpression of XPO1 in the cytoplasm was prominently related to advanced tumor stage, poor differentiation and a higher mitotic rate, while higher XPO1 expression in the nucleus was associated with cyclooxygenase-2 expression and worse OS." (PMID 31371628, 2019). "The XPO1 protein is elevated in ovarian carcinoma, glioma, osteosarcoma, pancreatic, cervical and gastric cancers and may have an important role as prognostic marker in solid and hematologic tumors." (PMID 25476752, 2014). "However, this phenomenon can be regarded as a sort of vulnerability exploited to restore FoxO signaling with inhibitors of nuclear export, as shown for FoxO1 with the XPO1 inhibitor selinexor in combination with cisplatin in ovarian cancer cells or for FOXO3 with psammaplysene in colon cancer cells." (PMID 30646603, 2019).
ovarian carcinoma (continued). "In particular, the overactivity of exportin 1 (XPO1/CRM1) in various cancers, such as ovarian carcinoma, glioma, and pancreatic cancer, highlights the need to target both NPC function and nuclear export processes in therapeutic strategies." (PMID 39459201, 2024). "XPO1 participates in the nuclear export of FOXO1, which decreases in platinum-resistant ovarian carcinoma." (PMID 34575598, 2021). "However, XPO7 knockdown has been implicated as a probable therapeutic target in conjunction with XPO1 knockdown in various neurodegenerative diseases such as dementia, amyotrophic lateral sclerosis (AML) and ovarian cancer and its overexpression in cancer results in poor outcomes." (PMID 31569391, 2019).
viral infection (30 papers, 2005 to 2026). "Aberrant XPO1 function is implicated in different diseases, including different types of cancers, inflammation, neurodegeneration and viral infections." (PMID 34832913, 2021). "Furthermore, XPO1-mediated nuclear export is associated with various types of disease, such as cancer, inflammation and viral infection." (PMID 38938904, 2022). "In this context, several conserved nuclear and nucleolar host factors required for virus infections in plants have been identified, such as importin α, fibrillarin and Exportin 1 (XPO1)." (PMID 40636018, 2025). "Our previous study showed that the IBN_N and CRM1_C domains of XPO1 interact with TuMV NIb to facilitate viral infection." (PMID 35058899, 2021). "Genes encoding host proteins essential for viral infection and replication, the co-receptor CCR5 and vRNA nuclear export factor XPO1, were also upregulated in lymph node infected cells." (PMID 28654687, 2017). "Depletion of one XPO1-dependent mRNA, dALDOA (Aldolase A), resulted in enhanced virus infection in Drosophila cells." (PMID 24550726, 2014). "Finally, transcription factors, small and large ribosomal subunits, exportin-1, and other transport proteins whose functions are related to the viral infection pathway are targeted by the bacterial GM’s proteins." (PMID 40227324, 2025). "XPO1 is considered a relevant target in different human diseases, particularly in hematological malignancies, tumor resistance, inflammation, neurodegeneration and viral infections." (PMID 34832913, 2021). "Thus, the emerging picture is that XPO1 is hugely important in viral diseases in humans and plants." (PMID 40828816, 2025). "Taken together, these data suggest that the nucleocytoplasmic transport of NIb is modulated by XPO1 through its interactions with the functional NLS and NES of NIb to promote viral infection." (PMID 35058899, 2021). "Inhibition of XPO1 either by RNAi or using the specific inhibitor LMB, which blocks the nuclear export function of XPO1, resulted in increased viral infection, which suggests the antiviral role of XPO1 is at the step of nuclear export." (PMID 24550726, 2014). "We found that XPO1 contains two NIb-binding domains, which recognize the NLS and NES of NIb, respectively, to mediate the nucleocytoplasmic transport of NIb and promote viral infection." (PMID 35058899, 2021). "On the other hand, viral infection does not affect the expression levels of XPO1 as observed in this study." (PMID 34012430, 2021). "Indeed, the expression of XPO1 increases during TBSV replication, which could lead to robust mobilization of nuclear antiviral factors to suppress viral infection." (PMID 40828816, 2025).
acute myeloid leukemia (25 papers, 2015 to 2026). Acute myeloid leukemia (AML) is a group of neoplasms arising from precursor cells committed to the myeloid cell-line differentiation. "In hematological malignancies, high levels of XPO1 are associated with shorter survival and are a poor prognostic factor in acute myeloid leukemia (AML)." (PMID 28196522, 2017). "We review the biological importance and the possibility of therapeutic targeting of Exportin 1 in acute myeloid leukemia (AML)." (PMID 40001478, 2025). "The nuclear export protein XPO1 interacts with nucleoporin 214 (NUP214) and has been implicated in the pathogenesis of SET::NUP214 acute myeloid leukemia (AML)." (PMID 40148556, 2025). "Selinexor inhibits XPO1 and has shown promising responses in multiple myeloma, acute myeloid leukemia (AML), and non-Hodgkin lymphoma patients." (PMID 39749030, 2024). "Overexpression of XPO-1 is common in many tumors, including acute myeloid leukemia (AML)." (PMID 36576532, 2023). "Indeed, a recurrent mutation in codon 571 of XPO1 gene has been reported in acute lymphoblastic leukemia (ALL) and in an adult with acute myeloid leukemia (AML) with CBL syndrome displaying XPO1 overexpression." (PMID 31088931, 2019).